DDAH1 (dimethylarginine dimethylaminohydrolase 1)
Diseases named in the same sentence as DDAH1 in open-access papers (continued):
Sharing a sentence is not in itself a finding about the gene and the disease.
Ureteral obstruction (1 paper, 2020). Obstruction of the flow of urine through the ureter. "Normal saline, ADMA, nonsense control siRNA, Ddah1 siRNA or Ddah2 siRNA was administered into the kidney through the left ureter in a mouse model of unilateral ureteral obstruction (UUO)." (PMID 32794631, 2020). "Knockdown of Ddah1 or Ddah2 in unilateral ureteral obstruction kidneys increased the amount of ADMA and inhibited the expression of fibrotic proteins." (PMID 32794631, 2020).
tumor (38 papers, 2002 to 2026). "Importantly, the upregulation of DDAH1 expression and consequent increased enzymatic activity may suggest a novel role for DDAH1 in tumor progression, providing novel diagnostic, and therapeutic opportunities for DDAH1 as a possible molecular drug target." (PMID 31993367, 2019). "Mice treated with both nimotuzumab (tail vein injection) and cisplatin (intraperitoneal injection) showed a significant reduction in tumor weight and volume, even in the presence of DDAH1 overexpression." (PMID 40538138, 2025). "Another important gene that is involved in cellular metabolism and at the same time plays an important role in the altered phenotype of the tumor cell is DDAH1." (PMID 37239828, 2023). "This method appears to be particularly useful for investigating the effects of pharmacological inhibition of DDAH1 on vasculogenic mimicry, tumour growth, and metastatic burden in xenograft models of cancer, specifically TNBC." (PMID 38138547, 2023). "To accurately evaluate the influence of AHCYL1 gene in the tumor microenvironments, we screened out three AHCYL1-associated genes (GNAI3, DDAH1, and NDC1) and established a risk score model." (PMID 35578598, 2022). "Tumor DDAH1 was upregulated in 11% of patients and downregulated in 33% (p = 0.050) and PRMT2 was upregulated in 15% of patients and downregulated in 33% (p = 0.120)." (PMID 34439753, 2021). "According to the Expression Atlas, the hypoxia-associated molecules CALB1, DDAH1, GAP43 and GPR37, as well as the tumor markers ART3, ENOL2 and FMOD and the tumor promoter NTNG1, are typically expressed in hematopoietic stem cells." (PMID 32466393, 2020). "A handful of studies have assessed the impact of DDAH1 inhibition by small molecules in cancer with promising results for inhibition of tumor growth, vasculature density, and VM." (PMID 31993367, 2019). "It is important to continue to unravel the mechanisms of DDAH1-mediated tumor angiogenesis and VM, and to further explore the potential of selectively inhibiting DDAH1 activity across different tumor types and stages." (PMID 31993367, 2019). "Our study also aimed to determine the effect of tumor hypoxia on DDAH-1 expression and the arginine/NO pathway." (PMID 28741166, 2017). "Downregulation of DDAH1 in GC, which is strongly correlated with tumor progression and clinical prognosis, merits further development as a diagnostic and prognostic biomarker." (PMID 28580735, 2017). "We anticipate that altered expression of miR-193b in breast tissue has a downstream effect on a network of genes (including DDAH1) that are critical for tumour pathology; further analysis of this miRNA-regulatory network is ongoing in our laboratory." (PMID 29070803, 2017). "In summary, our data show for the first time a high expression of DDAH1 in highly aggressive TNBC cell lines which is inversely correlated with a low expression of the tumour suppressor miR-193b." (PMID 29070803, 2017). "It has been reported that in tumor growth and tumor angiogenesis are involved different enzymes, such as iNOS, eNOS and DDAH-1." (PMID 24152986, 2013). "In the tumor immune microenvironment, DDAH1 overexpression inhibited the Wnt/GSK-3β signaling, which may enhance the recruitment of T cells." (PMID 35578598, 2022). "Collectively, these studies were the first to demonstrate the importance of DDAH1 in regulation of tumor vessel development and clearly demonstrated that DDAH1 expression leads to more hypoxic tumors, higher blood volume, better tumor perfusion, and increased number of functional vessels." (PMID 31993367, 2019). "Furthermore, in vivo studies using DDAH1 overexpression models have demonstrated increased tumor growth and corresponding increased tumor vasculature." (PMID 31993367, 2019). "Interestingly, the generation of an intermediate phenotype proposes an unidentified role for DDAH1 in the modulation of tumour growth." (PMID 29070803, 2017).
tumor (continued). "Taken together, these results indicate that DDAH1 may function as a tumor suppressor and downregulation of it may promote the development and progression of GC." (PMID 28580735, 2017). "In summary, this is the unprecedented study exploring the role of DDAH1 in GC and demonstrates for the first time that DDAH1 may act as a tumor suppressor specifically in GC." (PMID 28580735, 2017). "For instance, miR-21, which is highly expressed at tumor cells and promotes tumor growth by inhibiting the expression of dimethylarginine dimethylaminohydrolase 1 (DDAH1), phosphatase and tension homology deleted on chromosome ten (PTEN), and programmed cell death protein 4 (PDCD4)." (PMID 29027965, 2017). "A cohort of matched normal and tumour tissues with defined cancer staging and molecular subtype characterisation may provide further extensive information surrounding miR-193b/DDAH1 expression." (PMID 29070803, 2017). "To determine whether tumor hypoxia also influences the expression of DDAH-1, we performed this in vitro experiment: HepG2 cells were cultured under normoxic and hypoxic conditions." (PMID 28741166, 2017). "The findings provide background information that may be useful in the development of therapeutic strategies to manipulate DDAH1 expression in cardiovascular diseases or tumor angiogenesis." (PMID 24260221, 2013). "Still, a co-expression pattern of DDAH1 observed here might imply a tumor-promoting role." (PMID 34439753, 2021). "Moreover, while a strategy to enhance DDAH1 functionality is difficult to accomplish, any approaches to increasing the level or activity for tumor suppression may possess a therapeutic value." (PMID 28580735, 2017). "MiR-193b was demonstrated to negatively regulate tumor migration, invasion and metastasis through targeting urokinase type plasminogen activator (PLAU), dimethylaminohydrolase 1 (DDAH1), cyclin D1 (CCND1) and ETS1 in several cancer cell lines." (PMID 39972491, 2025). "Still, in line with the cancer-promoting activities attributed to DDAH1 and DDAH2, the expression ratio (tumor-to-adjacent) of DDAH2 tended to increase with cancer advancement, reflecting lymph node involvement." (PMID 32932854, 2020). "Some of them have been reported to play important roles in the development of tumor proliferation, apoptosis, and metastasis, such as IGF1R, MYBL2, POLE, and DDAH1." (PMID 32923489, 2020). "Tumor-adjacent tissue had higher expression of ARG1, DDAH1, and DDAH2 and lower NOS2 than patients-matched tumors." (PMID 32932854, 2020). "In contrast to DDAH1, the importance of DDAH2 in ADMA metabolism and thus tumor angiogenesis is still unclear." (PMID 31993367, 2019). "The proteomic clusters included tumor upregulated (PRDX3, APOA1, CLIC1) and downregulated (NFM, NDUS1, MDHC, ALDOC, STMN1, PEBP1, DDAH1, CN37) proteins." (PMID 25050814, 2014). "Pairwise analysis showed significantly downregulated expression of ARG1 (by 2.2-fold, p = 0.025), DDAH1 (by 1.4-fold, p = 0.016), and DDAH2 (by 1.6-fold, p = 0.005) and upregulated expression of NOS2 (by 2.6-fold, p = 0.003) in tumor as compared to adjacent, macroscopically normal tissue." (PMID 32932854, 2020). "On the contrary, DDAH1 in tumors exhibited a negative correlation with another angiogenic factor, FGF2, and DDAH2 in tumor-adjacent tissue—a positive association with an angiostatic IP-10." (PMID 32872669, 2020). "It was also associated with a tendency towards a higher expression of ARG1 and DDAH1 in noncancerous tumor-adjacent tissue." (PMID 32872669, 2020). "The expression of DDAH2 was significantly elevated, and that of DDAH1 non-significantly higher, exclusively in non-cancerous tumor-adjacent tissue." (PMID 32932854, 2020). "Activation of FXR with bile acids has been found to enhance tumor angiogenesis, however whether FXR alters DDAH1 expression in cancer cells has yet to be identified." (PMID 31993367, 2019).
tumor (continued). "It is important to note that immunofluorescence analysis of tumor tissue samples confirmed expression of DDAH1 localized to hepatocytes, and absent from neighboring endothelial cells of vascular structures." (PMID 31993367, 2019). "We found a higher expression of DDAH-1 in the HCC tumor samples compared to the corresponding non-tumorous liver tissue samples." (PMID 28741166, 2017). "More studies are needed to further unravel the mechanisms behind this pathway; for example, DDAH-1 knockdown experiments in rodents may gain more insight into the point of action of DDAH-1 in VEGF-dependent angiogenesis and tumor growth of HCC." (PMID 28741166, 2017). "Tumor and normal tissue microarray data (NPC, GSE12452, GSE53819; head and neck tumor, the Cancer Genome Atlas) revealed that AK4 was the only gene that was upregulated in both NPC and head and neck tumor samples compared to normal samples among the gene signatures (AK4, CPAMD8, DDAH1, and CRTR1)." (PMID 40593461, 2025). "For DDAH1, ARGI2, eIF4A3, PRDX3 and Par4 results have not shown significant changes in their respective mRNA levels in tumor compared to benign tissues (Data not shown)." (PMID 21347291, 2011). "Further, in-depth analysis of TCGA-PRAD data revealed significantly higher gene expression profiles for SLC12A2 (P = 0.025), DDAH1 (P < 0.0001), NDRG1 (P = 0.0013), APOE (P < 0.0001), YWHAZ (P = 0.0385), and GDF15 (P < 0.0001), in PCa tumor tissue compared with non-tumoral adjacent tissue." (PMID 33483585, 2021). "Thus, it appears that whilst DDAH1 metabolic activity is essential for the change in VEGF production, cell growth and tumor vascularity are not entirely dependent upon ADMA metabolism and VEGF production." (PMID 31993367, 2019). "Unfortunately, this study did not assess the effects of DDAH1 inhibition by Cl-NIO on specific tumor parameters, such as tumor cell viability and proliferation in vitro and/or in vivo growth of xenograft tumors derived from A375 cells, or assess the impact on angiogenesis." (PMID 31993367, 2019).
cancer (21 papers, 2013 to 2025). A tumor composed of atypical neoplastic, often pleomorphic cells that invade other tissues. "Taken together, they demonstrate that pharmacological inhibition of DDAH1 represents a novel, alternative strategy for the treatment of cancers associated with elevated DDAH1 expression and activity." (PMID 31993367, 2019). "Increased DDAH1 expression and NO production have been linked to multiple pathological conditions including cancer." (PMID 28580735, 2017). "More recently, a study has shown that DDAH1 can inhibit the renal fibrosis process via the Wnt/β‐catenin pathway, a well‐established crucial signaling event associated with a number of human diseases including cancer." (PMID 28580735, 2017). "In addition to these genes, there were other genes that were of interest and associated with cancer development or progression including dimethylarginine dimethylaminohydrolase 1 (DDAH1), kinesin family member 3A (KIF3A), and MUC1 which are all upregulated in the poor prognosis samples." (PMID 24634783, 2014). "In recent years, specific DDAH1 inhibitors have shown promise in suppressing abnormal neovascularization in cancer." (PMID 38525060, 2024). "In these experiments, ZST316 and ZST152 did not significantly degrade in the culture media and were able to successfully penetrate the cell membrane of cancer cells and inhibit DDAH1 intracellularly." (PMID 35164277, 2022). "Although studies are limited, the data to date suggests a basis for the development of DDAH1 inhibitors to be used as combined anti-angiogenic and anti-VM agents in cancer." (PMID 31993367, 2019). "The range of cancer types that display altered DDAH1 expression is significantly broader than that for DDAH2." (PMID 31993367, 2019). "Aside from the identification that DDAH1 expression is significantly altered in these cancers, only a handful of these studies undertook further analysis into the specific role and function of DDAH1 within each cancer context." (PMID 31993367, 2019). "As discussed here, DDAH expression (particularly DDAH1) is significantly altered in a number of different cancers." (PMID 31993367, 2019). "Additionally, western blotting and qPCR showed that DDAH1 overexpression significantly upregulated Sox2, Oct4, and Nanog, which are closely related to cancer cell stemness." (PMID 40538138, 2025). "According to GSEA analysis, DDAH1 affects cancer cell stemness." (PMID 40538138, 2025). "The pharmacological inhibition of DDAH1 is emerging as an attractive therapeutic strategy in disease states, e.g., septic shock and cancer, that are characterized by excessive local and/or systemic NO synthesis, primarily mediated by the inducible NOS isoform (iNOS)." (PMID 35164277, 2022). "Illogically, however, HIF1A displayed a weak but negative association with DDAH1 in multivariate analysis, an observation that requires further investigation, especially because targeting DDAHs has only recently been proposed as a novel antiangiogenic strategy in cancer." (PMID 32121248, 2020). "Regardless, based on current available knowledge the DDAH1 enzyme appears to be key for metabolism of ADMA/NMMA and thus more relevant in regard to the treatment of cancer through the ADMA/NO pathway." (PMID 31993367, 2019). "When we overexpressed active Ras with ad-Ras G12V infection (MOI 20) in HUVEC with DDAH1 knockdown, we found that active Ras increased VEGF expression in the control cells, which is consistent with a previous study in cancer cells." (PMID 24260221, 2013). "The differential expression of DDAH1 and PDIA6 in GSTP1 knockdown PDAC cells is particularly intriguing, as both are involved in redox homeostasis and are frequently upregulated in various cancers." (PMID 40719618, 2025). "This study identified DDAH1 as a prognostic marker and a potential therapeutic target for nimotuzumab to overcome treatment failure and chemoresistance in LANPC and other EGFR‐positive cancers." (PMID 40538138, 2025).
cancer (continued). "DDAH1 and DDAH2 expression in human cancer tissues and cell lines." (PMID 31993367, 2019). "Interestingly, with the exception of these three cancers, the expression of DDAH1 and DDAH2 does not change in the same direction." (PMID 31993367, 2019). "Pending the results of animal studies, the use of DDAH1 inhibitors, alone or in combination with traditional anti-angiogenic therapies such as anti-VEGF drugs, might represent a novel strategy to suppress both angiogenesis and VM, key factors in early cancer development and dissemination." (PMID 31993367, 2019).
cardiovascular disease (11 papers, 2011 to 2024). "Dimethylarginine dimethylaminohydrolase 1 (DDAH1) protects against cardiovascular disease by metabolising the risk factor asymmetric dimethylarginine (ADMA)." (PMID 37296100, 2023). "Recent discoveries have highlighted the SNPs of Ddah1 was associated with cardiovascular disease and diabetes." (PMID 35013196, 2022). "Emerging evidences suggest that plasma ADMA levels are significantly associated with SNPs (Single Nucleotide Polymorphisms) in Ddah1, which contributed to cardiovascular diseases and diabetes." (PMID 35013196, 2022). "Some previous studies confirmed that Ddah1 plays a crucial role in the clearance of asymmetric dimethylarginine and monomethyl arginine, which are strongly associated with premature cardiovascular disease and death." (PMID 33365332, 2020). "The endogenous NO synthase inhibitor asymmetric dimethylarginine (ADMA) is metabolized by DDAH1 (dimethylarginine dimethylaminohydrolase 1) and elevated in cardiovascular disease." (PMID 38226470, 2024). "In humans, the DDAH-1 isoform is known to metabolize endogenous asymmetric dimethylarginine (ADMA) and monomethyl arginine (l-NMMA), with ADMA proposed to be a putative marker of cardiovascular disease." (PMID 27187323, 2016). "Together these findings suggest that increasing DDAH1 expression through FXR activation could be an important therapeutic target for treating reduced NO bioavailability in CHF and other cardiovascular diseases." (PMID 23878601, 2013). "Thus, elevated DDAH1 activity could be an important therapeutic target for increasing NO bioavailability in CHF and other cardiovascular diseases." (PMID 23878601, 2013).
infection (6 papers, 2011 to 2023). The state of being infected such as from the introduction of a foreign agent such as serum, vaccine, antigenic substance or organism. "DDAH knockdown HUVECs were generated by infection of lentivirus vectors which express control shRNA, DDAH1 shRNA, or DDAH2 shRNA." (PMID 37296100, 2023). "Without any difference in bacterial entry, knockdown of DDAH1 led to significantly higher infection levels compared to the scrambled siRNA control." (PMID 34804992, 2021). "We found that DDAH1 counteracts infection by Listeria monocytogenes, likely via effects on NO production as a potential mechanism underlying the antilisterial activity of RNF213." (PMID 34804992, 2021). "To investigate this, we infected HeLa cells with reduced or enhanced expression levels of DDAH1 with Listeria at a multiplicity of infection (MOI) of 25, measuring the effect of CYR61 and MVP in parallel." (PMID 34804992, 2021). "Further, we found that the increased VEGF expression produced by DDAH1 overexpression was blocked by Ad-dnRas infection or manumycin A treatment, both of which also abolished the Akt activation." (PMID 24260221, 2013). "We found that DDAH1 overexpression caused an increase of VEGF expression, and that Ras inhibition by Ad-dnRas infection or the inhibitor manumycin A blocked the increase in VEGF expression." (PMID 24260221, 2013). "DDAH1 has not directly been linked to infection, but as an important regulator of nitric oxide (NO) generation, the protein is an interesting target since NO plays an important role in immune defence as well as vascular regulation." (PMID 34804992, 2021). "Similar to RNF213, a previous genome-wide siRNA screen ranked DDAH1 and CYR61 as protective host factors during infection with Listeria monocytogenes (further referred to as Listeria), a facultative intracellular bacterial model pathogen." (PMID 34804992, 2021). "For further work we decided to focus on DDAH1 and CYR61 given their strong downregulation upon RNF213 knockdown and potential role in the host response to infection." (PMID 34804992, 2021). "DDAH-1 and, to a lesser extent, DDAH-2 immunoreactivities were observed in several brain areas (cortex, hippocampus, amygdala) and notably in the hypothalamic and thalamic groups of nuclei in healthy and infected rat (at D10 and D16 post-infection) groups." (PMID 21408057, 2011).
kidney disease (3 papers, 2012 to 2021). "It was already shown in 1996 that NO ameliorates UUO-induced fibrosis in rats and inhibition of DDAH1 expression/activity resulting in NOS impairment might be responsible for complications observed in different renal diseases." (PMID 27610006, 2016). "Substitution of DDAH1 protein or enhancement of its activity may become a novel treatment strategy for renal diseases." (PMID 23110194, 2012).